PON1 (paraoxonase 1)
Diseases named in the same sentence as PON1 in open-access papers (continued):
Sharing a sentence is not in itself a finding about the gene and the disease.
endometrial cancer (6 papers, 2020 to 2024). Primary or metastatic malignant neoplasm involving the endometrium (mucous membrane that lines the endometrial cavity). "We noted statistically lower levels of PON1 in patients with endometrial cancer, even accounting for a potential risk factor for endometrial cancer, which is body mass index, by including this in the control group patients of similar BMI." (PMID 36290747, 2022). "Reduced PON1 activity was reported in different types of female cancer such as breast, ovarian, and endometrial cancer." (PMID 38125616, 2024). "In the group of premenopausal patients, we found significantly lower median concentrations of PON1 in the group of patients with endometrial cancer as compared to the group with normal endometrium (p = 0.01)." (PMID 36290747, 2022). "To date, there have been limited publications reporting the serum PON1 concentrations, activity, or expression in patients with endometrial cancer." (PMID 36290747, 2022). "In case of postmenopausal patients, statistically significantly lower median PON1 levels were noted in patients with endometrial cancer compared to the control group (p = 0.002)." (PMID 36290747, 2022). "The results presented in this paper point to PON1 as a significant prognostic factor in endometrial cancer." (PMID 36290747, 2022). "We evaluated paraoxonase-1 and pentraxin-3 in the diagnosis and prognosis of endometrial cancer." (PMID 36290747, 2022). "The decrease in PON1 activity was found in the blood serum of patients with genital tract neoplasms, including endometrial cancer, with colorectal and bladder cancers, while the lower PON1 concentration was observed in patients with tumor recurrence compared with patients without relapse." (PMID 34885171, 2021). "PON1 may be considered a potential biomarker in the diagnosis of endometrial cancer." (PMID 36290747, 2022). "PON1 could be used as a marker in the diagnosis of endometrial cancer." (PMID 36290747, 2022). "In our study, we noted a strong relationship between PON1, PTX3 and endometrial cancer." (PMID 36290747, 2022). "We found statistically significant differences in the median serum levels for PON1 and PTX3 in the group of endometrial cancer, when compared to the group of normal endometrium (without taking into account the hormonal status of the patients)." (PMID 36290747, 2022).
hypothyroidism (6 papers, 2019 to 2024). Abnormally low levels of thyroid hormone. "Interestingly, the results found in dogs are opposite to those found in humans, where a decrease in PON-1 is commonly associated with hypothyroidism." (PMID 38662314, 2024). "However, a recent study has shown that both cholesterol efflux and activity of HDL-associated enzyme paraoxonase 1 (PON1) are decreased in patients with overt hypothyroidism, thus implicating diminishing of HDL functionality." (PMID 31920978, 2019). "On the other hand, an increase in PON-1 was found in RBCs lysates of dogs with hypothyroidism compared to the control group." (PMID 38662314, 2024). "Meanwhile, RBCs lysates showed a significant increase in FRAP and PON-1 in dogs with hypothyroidism." (PMID 38662314, 2024). "The positive correlation between T3 and SOD and PON 1 is often reported in hypothyroidism because of the important role of thyroid hormones in lipid metabolism and the antioxidant function of these enzymes." (PMID 36984774, 2023). "An increase in three antioxidant biomarkers (TEAC, PON-1, and GPx) was found in serum of dogs with hypothyroidism." (PMID 36732758, 2023). "Namely, there was an increase of antioxidants (TEAC, PON-1, and GPx) and oxidants (TOS, POX-Act, and d-ROMs) in serum of dogs and an increase in TBARS: protein ratio in dogs with hypothyroidism in comparison to healthy dogs." (PMID 36732758, 2023). "Results showed a significantly higher TEAC, PON-1, GPx, TOS, POX-Act, and d-ROMs, and a significantly lower AOPP in serum of dogs with hypothyroidism." (PMID 36732758, 2023). "On the other hand, WB, RBCs lysates and serum concentrations of PON-1 were higher in dogs with hypothyroidism compared to dogs with non-thyroidal diseases (p = 0.012, p ≤ 0.0001, and p = 0.001, respectively)." (PMID 38662314, 2024). "TEAC and PON-1 showed significantly higher values in dogs with hypothyroidism compared to dogs with non-thyroid diseases (P = 0.0486 and P = 0.0069, respectively) and healthy dogs (P = 0.0420 and P = 0.0074, respectively)." (PMID 36732758, 2023). "In patients with hypothyroidism, high plasma levels of NO and malondialdehyde (MDA), a marker of oxidative stress, were measured in hepatic vein, along with lower activity of paraoxonase-1 (PON-1), a liver enzyme with antioxidant features." (PMID 31640265, 2019). "Therefore, the elevation of cholesterol that usually appears in canine hypothyroidism could imply an increase in HDL and subsequently in PON-1." (PMID 36732758, 2023).
liver dysfunction (6 papers, 2018 to 2025). "One important biomarker indicative of the severity of liver dysfunction or Dysfunction-Associated Steatotic Liver Disease is paraoxonase, specifically the activity of the enzyme paraoxonase-1 (PON1)." (PMID 40005465, 2025). "However, the findings presented herein advocate for a cautious interpretation of PON-1 activity values, especially in the case of hepatopathy and, more significantly, when liver failure is suspected." (PMID 39409835, 2024). "No other significant associations were identified between PON1-related parameters and the histological features of liver dysfunction, and none of these variables were usable as predictors of NASH." (PMID 38136158, 2023). "In people with hepatopathies, a significant negative correlation between ALT and PON-1 activities exists, with the PON-1 activity decreasing with increased severity of liver damage." (PMID 39409835, 2024).
multiple myeloma (6 papers, 2005 to 2025). "Decreased activity of the antioxidant molecules ARE and PON1 are considered to be biomarkers of poor prognosis in multiple myeloma patients as markers of poor prognosis." (PMID 35854269, 2022). "The most significant AUC-values were found when comparing pre-malignant myeloma to high bone disease for both C4 and PON1, with values of 0.747 and 0.682 respectively." (PMID 25322877, 2014).
osteoporosis (6 papers, 2014 to 2024). A condition of reduced bone mass, with decreased cortical thickness and a decrease in the number and size of the trabeculae of cancellous bone (but normal chemical composition), resulting in increased fracture incidence. "A previous study reported PON1 polymorphisms to modify the association between lycopene and oxidative stress parameters and bone turnover markers, and thus moderated the risk of osteoporosis." (PMID 35646794, 2022). "We found that serum paraoxonase/arylesterase 1 (PON1) was positively associated with osteoporosis in East Asian, while cholinesterase (BCHE) was significantly associated with LS‐BMD, and apolipoprotein L1 (APOL1) was significantly associated with FN‐BMD and heel eBMD in European population." (PMID 37970652, 2024). "A previous study showed that PON1 polymorphisms modified the association between serum concentrations of lycopene and oxidative stress parameters and bone turnover markers and therefore, decreased the risk of osteoporosis." (PMID 35646794, 2022). "In addition, there were studies which had confirmed that the PON1 gene polymorphism was associated with osteoporosis." (PMID 35646794, 2022). "Osteoporosis patients showed reduced serum PON1 activity when compared with healthy individuals." (PMID 38099525, 2024). "Therefore, PON1 SNVs may be critical in bone metabolism and osteoporosis." (PMID 37107290, 2023).
acute pancreatitis (5 papers, 2012 to 2023). An acute inflammatory process that leads to necrosis of the pancreatic parenchyma. "It has been previously reported that serum PON-1 decreases in inflammatory processes and in some devastating diseases such as parvoviral enteritis, leishmaniosis, and acute pancreatitis." (PMID 37368717, 2023). "The activity of PON-1 has been found to be significantly reduced in dogs with leishmaniosis, ehrlichiosis, acute pancreatitis, parvovirus enteritis, and endotoxemia." (PMID 36669034, 2023). "Unal et al41showed significantly decreased PON1 activity and positive correlation to HDL level, with significantly increased malondialdehyde levels in acute pancreatitis among Wistar albino rats." (PMID 32939514, 2020). "The current study was undertaken to investigate the polymorphic sites in the PON1 gene (rs662) and APOA1 gene (rs670 and rs5069) in individuals suffering from acute pancreatitis, from which data was hitherto not available." (PMID 36360205, 2022).
bipolar disorder (5 papers, 2020 to 2024). A disorder of the brain that causes unusual shifts in mood, energy, activity levels and the ability to carry out day-to-day tasks. "In the first one, the authors underlie that the odds of bipolar disorder were increased by the QQ genotype in smokers, suggesting that PON1 Q192R polymorphisms mediate the effects of smoking on bipolar disorder." (PMID 35893041, 2022). "A second significant finding of the first study is that smoking interacts with the functional PON1 genotypes to predict bipolar disorder and decreases plasma PON1 activity." (PMID 35893041, 2022).
coronary stenosis (5 papers, 2009 to 2024). Narrowing of the coronary artery lumen diameter. "The serum PON1 activity was determined using a spectrophotometry-based assay in 186 patients with diagnostic coronary angiography, in which coronary stenosis severity was graded and clinically defined as single- or multi-vessel stenosis >50%." (PMID 28038449, 2017). "In a recent study; including PON1 genotyping, activity and lipid profile and their association with significant coronary stenosis (SCS) in Tunisian population, PON1 activity was lower in patients with SCS than in controls." (PMID 25551104, 2014). "Compared to healthy controls, significantly lower levels of PON-1 and SRB-1 were observed, with lower values in those angiographically diagnosed with the maximum severity of coronary stenosis." (PMID 39336967, 2024). "Furthermore, PON-1 may have prognostic significance in severe coronary artery stenosis." (PMID 39336967, 2024). "However, whether PON1 activity can predict the degree of coronary stenosis remains unknown." (PMID 28038449, 2017).
dyslipidaemia (5 papers, 2014 to 2024). "The PON1 rs854560 TT genotype was also associated with dyslipidaemia and cardiovascular diseases, as well as mortality in haemodialysis patients." (PMID 39062650, 2024). "We analysed the PON1 gene (PON1) polymorphisms and serum PON1 (paraoxonase) activity concerning dyslipidaemia and related cardiovascular diseases and mortality to show how they associate under uremic conditions modified by maintenance HD treatment." (PMID 33762698, 2021). "Dyslipidaemia, whether due to familial hypercholesterolaemia or hypertriglyceridaemia, is associated with diminished PON1 activity with perhaps its most profound decreases occurring in familial dysbetalipoproteinaemia [unpublished observation]." (PMID 36873390, 2023). "Normalized serum PON1 (paraoxonase) activity positively associates with atherogenic dyslipidaemia." (PMID 33762698, 2021). "Our study indicates that PON1 SNVs correlate with HD patients' clinical parameters (dyslipidaemia, ICS, cardiovascular mortality)." (PMID 33762698, 2021). "Only the univariate analyses indicated inverse correlations between serum PON1 activity and mixed dyslipidaemia by K/DOQI and serum TG concentration." (PMID 33762698, 2021). "The normalized serum PON1 activity positively correlated with atherogenic dyslipidaemia (ẞ 0.67 ± 0.25, P = 0.008)." (PMID 33762698, 2021). "Exploring dyslipidaemia, atherosclerotic diseases, and cardiovascular mortality, possibly positively influenced by favourable PON1 SNVs and optimal serum PON1 activity, we aimed to comment on PON1 and PON1 usefulness as future therapeutic targets in the management of HD patients." (PMID 33762698, 2021). "Therefore, decreased PON1 activity plays an essential role in dyslipidaemia and worse dialysis patients' outcomes." (PMID 33762698, 2021). "Associations of non-normalized serum PON1 activity with simultaneously shown clinical variables were limited to mixed dyslipidaemia by K/DOQI guidelines and serum TG levels in unadjusted analyses." (PMID 33762698, 2021). "In our study, the results of associations between PON1 SNVs and atherogenic dyslipidaemia seem to be not influenced by lipid-modifying therapy." (PMID 33762698, 2021). "The PON1/HDL-cholesterol ratio correlated positively with male sex, cigarette smoking, presence of atherogenic dyslipidaemia, and values of the TG/HDL-cholesterol ratio." (PMID 33762698, 2021). "As dyslipidaemia, increased oxidative stress and unfavourable adipokine profile was found in the NDO patients together with absence of altered paraoxonase activities, we evaluated the PON1 phenotype distribution and the allelic frequencies." (PMID 24702860, 2014).
endometriosis (5 papers, 2013 to 2025). The growth of functional endometrial tissue in anatomic sites outside the uterine body. "The authors conclude that PON-1 activity can be used as a diagnostic test to detect endometriosis." (PMID 23799909, 2013). "We aimed to compare the serum levels of PON-1 activity in women with endometriosis in different stages of the disease (minimal/mild and moderate/severe)." (PMID 23799909, 2013). "PON-1 activity was significantly higher in women with moderate/severe endometriosis than in women with minimal/mild disease and controls, and in women with minimal/mild endometriosis compared with control groups (P < 0.0001, for all)." (PMID 23799909, 2013). "Considering the complex cellular and molecular mechanisms involved in endometriosis formation and progression, we aimed to compare the serum levels of PON-1 activity in women with endometriosis in different stages of the disease (minimal/mild and moderate/severe)." (PMID 23799909, 2013).
liver cancer (5 papers, 2020 to 2025). An epithelial or non-epithelial malignant neoplasm that arises from the liver. "Increased expression of PON1 was correlated with higher survival probability in liver cancer (data available from The Human Protein Atlas, version 23.0)." (PMID 40149317, 2025). "Among the four genes, C2orf27A and IGF2R were found to be positively correlated and CFB and PON1 were negatively correlated with the stage and tumor grade of liver cancer." (PMID 33495404, 2021). "Kaplan–Meier analysis subsequently showed that C2orf27A and IGF2R were negatively correlated with the survival time of liver cancer patients, whereas CFB and PON1 were associated with favorable survival times." (PMID 33495404, 2021). "This study has clarified the existence of potential biomarkers, such as the two glycopeptides of PON1 in AFP-negative liver cancer." (PMID 33889548, 2021). "Down-regulation of PON1 may suggest that patients with liver cancer have difficulty in survival." (PMID 37589009, 2023). "Furthermore, PON1 is potentially related to the MVI of liver cancer; therefore, given the correlation between MVI and sorafenib efficacy, PON1 might play a crucial role in the development of SR by influencing MVI, which agrees with the findings of the present study." (PMID 33495404, 2021).
pancreatic cancer (5 papers, 2016 to 2024). "Remarkably, polymorphisms in thePON1 gene have been associated with increased PON1 expression in a subset of pancreatic cancer patients." (PMID 33274048, 2020). "Such postulation can be generally supported by studies currently linking PON1 genotypes to lung, endometrial, ovarian, gastric, and pancreatic cancers." (PMID 28467805, 2017). "In patients with pancreatic cancer, HDL and PON1 levels were lower than in healthy subjects." (PMID 27182229, 2016).
poisoning (5 papers, 2009 to 2025). A condition or physical state produced by the ingestion, injection, inhalation of or exposure to a deleterious agent. "Animals deficient in PON1 (knockout animals) are more susceptible to OP-poisoning as compared to their wild-type counterparts, and administration of exogenously purified PON1 has showed protection against OP-poisoning." (PMID 26829396, 2016). "Animals deficient in PON1 (knockout animals) have been found to be more susceptible to OP-poisoning compared to their wild-type counterpart and administration of purified PON1 has been shown to provide protection against OP-poisoning in various animal models." (PMID 25386619, 2014). "The in vivo efficacy of recombinant PON1 and BL-3050 were tested with an animal model of chlorpyrifos-oxon poisoning." (PMID 19922610, 2009). "Paraoxonase 1 (PON1) is an enzyme that protects against vascular disease and organophosphate poisoning." (PMID 39996801, 2025). "Paraoxonase 1 (PON1), which was initially described as an enzyme providing protection from pesticide poisoning, has been confirmed as playing a role in a wide variety of human illnesses, including cardiovascular disease." (PMID 32961879, 2020).
renal carcinoma (5 papers, 2012 to 2021). A carcinoma arising from the epithelium of the renal parenchyma or the renal pelvis. "The R allele of paraoxonase-1 gene Q192R polymorphism might protect against renal cancer." (PMID 26537097, 2015). "Paraoxinase 1 (PON1) was recently described to be involved in the development of sunitinib resistance in renal cancer." (PMID 34069743, 2021). "Hypermethylated PON1 promoted migration, invasion and proliferation of sunitinib‐resistance renal cancer cells and arrested more cells in G0/G1 phase." (PMID 31400051, 2019). "In this study, our aim was to exploring the influences of DNA methylation of PON1 on cell proliferation, migration and apoptosis of renal cancer cells." (PMID 31400051, 2019). "In detail, the demethylation of PON1 inhibited the migration, invasion and proliferation of renal cancer cells and also arrested more cells in G0/G1 phase." (PMID 31400051, 2019). "In addition, the effect of PON1 on renal cancer cells was verified by experiments in vivo." (PMID 31400051, 2019). "In short, this is the first study on the hypermethylated PON1 involved in the development of RCC, and it showed DNA methylation was one of the key parts in the proliferation of renal cancer cells especially the RCC cells." (PMID 31400051, 2019).
anemia (4 papers, 2012 to 2025). A reduction in the number of red blood cells, the amount of hemoglobin, and/or the volume of packed red blood cells. "EPObeta and iron treatment of anemia of CRF promotes changes in serum PON1 activity and concentration that suggest a beneficial effect on oxidative stress." (PMID 22523692, 2012).
Anxiety (4 papers, 2021 to 2025). Intense feelings of nervousness, tension, or panic often arise in response to interpersonal stresses. "rs705381, combined with another variant of the acetylcholinesterase-paraoxonase 1 locus, significantly contributes to the reduced PON1 expression and trait-anxiety measures of healthy subjects." (PMID 38275640, 2023). "PON1 rs854560 AA was associated with a YBOCS obsessions subtotal (p = 0.038), BSPS (p = 0.018), and Zung anxiety (p = 0.005)." (PMID 38275640, 2023).